CLPP (caseinolytic mitochondrial matrix peptidase proteolytic subunit)
Diseases named in the same sentence as CLPP in open-access papers (continued):
Sharing a sentence is not in itself a finding about the gene and the disease.
Obesity (5 papers, 2019 to 2023). Accumulation of substantial excess body fat. "In contrast, KO mice for the ClpP gene, which codes for an important UPRmt effector, show a lower prevalence of obesity compared to wild-type ClpP mice and also have improved glucose homeostasis presenting a fasting-like phenotype." (PMID 36982728, 2023). "It remains to be seen if targeting the ClpP protease using specific inhibitors in fat tissues will help combating obesity-related disorders in humans." (PMID 36389399, 2022). "Interestingly, whole-body deletion of ClpP in mice was recently reported to protect against diet-induced obesity and insulin resistance." (PMID 30877431, 2019). "Furthermore, analyses of the phenotype of ClpP KO mice revealed the unknown function of ClpP in the energy metabolism of mammals since ClpP KO mice are protected from high-fat diet–induced obesity, insulin resistance, and glucose intolerance." (PMID 37660922, 2023).
ovarian carcinoma (5 papers, 2022 to 2025). A malignant neoplasm originating from the surface ovarian epithelium. "After revealing that CLPP is involved in the DDP resistance of ovarian cancer, we investigated the underlying mechanism for its effect on DDP resistance." (PMID 38419499, 2024). "In ovarian cancer, ClpP is stabilized by HSPA8, a chaperone protein belonging to the HSP70 family, and contributes to cisplatin resistance, indicating a potential role in the regulation of chemoresistance." (PMID 41155556, 2025). "This suggests that CLPP can regulate mitochondrial autophagy in cisplatin-resistant ovarian cancer cells." (PMID 38419499, 2024). "In this study, 2 DDP-resistant ovarian cancer cell lines were established, and CLPP was found to be significantly downregulated in DDP-resistant cells." (PMID 38419499, 2024). "Taken together, our findings suggest that HSPA8-mediated stability of the CLPP protein regulates mitochondrial autophagy in DDP-resistant ovarian cancer cells." (PMID 38419499, 2024). "Here, we establish two DDP-resistant ovarian cancer cell lines and find that caseinolytic protease P (CLPP) level is significantly downregulated in DDP-resistant cell lines compared to wild-type ovarian cancer cell lines (SK-OV-3 and OVcar3)." (PMID 38419499, 2024). "In summary, we successfully generated 2 DDP-resistant ovarian cancer cell lines and found that CLPP increased the DDP resistance of ovarian cancer cells by inhibiting mitophagy and promoting cellular stress." (PMID 38419499, 2024). "Taken together, these results suggest that HSPA8 mediates cisplatin-resistant ovarian cancer cell phenotypes via CLPP-dependent signaling." (PMID 38419499, 2024). "In conclusion, CLPP increases DDP resistance in ovarian cancer by inhibiting mitophagy and promoting cellular stress." (PMID 38419499, 2024). "In ovarian cancer, the activation of CLPP by small molecules significantly inhibits cellular proliferation, adhesion, and metastasis and induces G1 phase arrest, cellular stress, and cell death." (PMID 38419499, 2024). "In this study, we examined the effect of CLPP on mitophagy in ovarian cancer cells undergoing DDP treatment." (PMID 38419499, 2024). "After determining the effects of CLPP in wild-type ovarian cancer cells, we subsequently investigated the effects of CLPP in cisplatin-resistant ovarian cancer cells." (PMID 38419499, 2024). "ClpP enhances resistance to cisplatin in ovarian cancer cells by suppressing mitophagy and exacerbating cellular stress." (PMID 39261452, 2024). "Our data showed thatCLPP knockdown promoted the expressions of PINK1, Parkin, and LC3II/I proteins in wild-type ovarian cancer cells, while CLPP overexpression decreased these levels of expression." (PMID 38419499, 2024). "In this study, we explored the effects of CLPP on mitophagy in wild-type or DDP-resistant ovarian cancer cells." (PMID 38419499, 2024). "Knockdown of ClpP in ovarian cancer cells reduced ONC201 mediated the anti-tumor activity and cellular stress." (PMID 35372029, 2022). "However, overexpression of ClpP in ovarian cancer cells reduces cell motility and represses cell migration and invasion by inducing mitochondrial respiratory chain disorder." (PMID 39261452, 2024). "The dynamic effects of the HSPA8/CLPP axis in ovarian cancer cells are also examined." (PMID 38419499, 2024). "Similarly, HSPA8 reduces CLPP protein stability in ovarian cancer cells and affects ovarian cancer cell drug resistance and survival via CLPP." (PMID 39578715, 2024). "However, the role of CLPP in DDP resistance in ovarian cancer remains unclear." (PMID 38419499, 2024). "Our study reveals a novel regulatory axis of DDP resistance in ovarian cancer cells and suggests promising targets (i.e., HSPA8, CLPP, and mitochondrial protein homeostasis) for overcoming DDP resistance." (PMID 38419499, 2024).
ovarian carcinoma (continued). "Furthermore, our data showed that overexpression of CLPP could reduce the levels of cellular and mitochondrial autophagy in cisplatin-resistant cells, increase the ROS levels and apoptosis rates of ovarian cancer cells, and thus improve the drug sensitivity of ovarian cancer cells." (PMID 38419499, 2024). "Our results demonstrated that knockdown ofCLPP significantly increased the IC50 values of wild-type ovarian cancer cells, and the IC50 values of DDP-resistant ovarian cancer cells were decreased by CLPP overexpression, which is consistent with the tumor-suppressive effects of CLPP." (PMID 38419499, 2024). "Next, we investigate the functions of CLPP in DDP-resistant and wild-type ovarian cancer cells using various assays, including cell counting kit-8 assay, western blot analysis, immunofluorescence staining, and detection of reactive oxygen species (ROS) and apoptosis." (PMID 38419499, 2024).
triple-negative breast carcinoma (5 papers, 2022 to 2025). An invasive breast carcinoma which is negative for expression of estrogen receptor (ER), progesterone receptor (PR), and human epidermal growth factor receptor 2 (HER2). "We report that ONC201 and highly potent second generation ClpP agonists (TR-57, TR-107), promote induction of senescence in triple-negative breast cancer (TNBC) cell lines." (PMID 41333384, 2025). "ClpP activation perturbs many metabolic pathways across proteomic, transcriptomic, and metabolomic landscapes in triple-negative breast cancer cells." (PMID 37063293, 2023). "TR107 exhibits nanomolar antitumor activity against triple-negative breast cancer SUM159 and MDA-MB231 cells and degrades the essential proteins of oxidative phosphorylation and tricarboxylic acid cycle pathways via ClpP by generating a ClpP-KO cell line." (PMID 40395852, 2025). "In this study, we utilized a multi-omics approach to identify the ClpP-dependent proteomic, transcriptomic, and metabolomic changes resulting from ONC201 or the TR compound TR-57 in triple-negative breast cancer cells." (PMID 37063293, 2023).
breast adenocarcinoma (4 papers, 2016 to 2022). "High levels of CLPP expression were associated with shortened distant metastasis-free survival in patients with breast adenocarcinoma." (PMID 36388465, 2022). "Importantly, high levels of ClpP expression were associated with shortened distant metastasis-free survival in patients with breast adenocarcinoma and uveal melanoma and in abbreviated relapse-free survival in lung adenocarcinoma." (PMID 27389535, 2016). "Conversely, ClpP levels were increased in histotypes of breast adenocarcinoma compared to normal epithelium." (PMID 27389535, 2016). "In contrast, in the breast adenocarcinoma cell line MCF-7, ClpP is highly expressed but the loss of ClpP had minimal effects on cell proliferation which suggests the importance of ClpP expression in cancer pathology may be cell-type specific." (PMID 33922062, 2021). "In addition, increased ClpP expression is correlated with poor prognosis and lower metastasis-free survival in patients with breast adenocarcinoma, uveal melanoma, and lung adenocarcinoma." (PMID 33922062, 2021). "First, ClpP was prominently upregulated in breast adenocarcinoma MCF-7 cells, compared to non-tumorigenic breast epithelial MCF-10A cells." (PMID 27389535, 2016). "In addition, silencing of ClpP or ClpX minimally reduced proliferation of non-metastatic breast adenocarcinoma MCF-7 cells, and non-tumorigenic breast epithelial MCF-10A cells were not affected." (PMID 27389535, 2016).
Insulin resistance (4 papers, 2019 to 2025). Increased resistance towards insulin, that is, diminished effectiveness of insulin in reducing blood glucose levels. "In addition, ClpP knock-out mice compared with wild-type mice showed a decrease in insulin resistance, together with improved glucose homeostasis in liver, skeletal muscle and adipose tissue." (PMID 36982728, 2023).
melanoma (4 papers, 2019 to 2025). A malignant, usually aggressive tumor composed of atypical, neoplastic melanocytes. "The most significant differences in melanoma are NOMO1, PIGT, VKORC1, PDIA5 and DDX11, and the most significant differences in uterine cancer are CTU2, EMC8, TUBG1, CLPP and LONP1." (PMID 34951103, 2022). "In ClpP−/− mice, we previously observed an accumulation of mtDNA, whereas mtDNA was lower upon knockdown of LonP1 in B16F10 melanoma cells." (PMID 31547314, 2019).
pneumonia (4 papers, 2021 to 2026). An acute, acute and chronic, or chronic inflammation focally or diffusely affecting the lung parenchyma, caused by an infection in one or both of the lungs (by bacteria, viruses, fungi, or mycoplasma.). "ClpP is implicated for both of these diseases, and HtrA is implicated in pneumonia; the question of direct impact on host proteins or indirect effects of these proteases remains." (PMID 33660565, 2021). "ClpP protease is important for the development of S. aureus pneumonia; therefore, we constructed a pneumonia model of S. aureus-infected mice and treated them with a subcutaneous injection of nepetin." (PMID 35363605, 2022). "ClpP is an essential protein that regulates homeostasis and stress in S. aureus and is critical for the developing pneumonia in S. aureus infections." (PMID 35319277, 2022). "Immunization with ClpP increased the survival time of mice infected intraperitoneally with S. pneumoniae and provided protection in conjunction with two other pneumococcal proteins in mouse pneumonia and sepsis models." (PMID 33660565, 2021).
skin abscess (4 papers, 2019 to 2025). "In contrast, clpX and clpP deletion mutants of S. aureus are highly attenuated in the skin abscess model, likely due to their control of several major staphylococcal virulence factors." (PMID 40208051, 2025). "Knockout of the clpP gene in S. aureus weakened virulence in a murine skin abscess model, and a similar action was obtained after suppression activity of ClpP by β-lactones." (PMID 40588743, 2025). "In addition, in a mouse skin abscess model, the inactivation of clpX and clpP completely reduced the formation of abscesses." (PMID 35369527, 2022). "Follow-up experiments enlarged the scope to ClpP itself, when clpP- and clpX-deficient mutants showed lack of virulence in a murine skin abscess model." (PMID 31067645, 2019).
Azoospermia (3 papers, 2021 to 2024). Absence of any measurable level of sperm,whereby spermatozoa cannot be observed even after centrifugation of the semen pellet. "Meiotic arrest in testis with consequent azoospermia as upon CLPP depletion was observed in other mitochondriopathy mouse models only when mtDNA levels were manipulated." (PMID 35954215, 2022). "Data from one PRLTS3 male patient and CLPP-depleted mice show also complete male infertility with azoospermia to form part of the clinical picture." (PMID 35954215, 2022).
brain tumors (3 papers, 2021 to 2025). "Future trials should integrate metabolic and genetic biomarkers to refine ClpP-directed strategies in brain tumors." (PMID 41155556, 2025). "This underscores that therapeutic modulation of ClpP must be context-specific, with activators in brain tumors and inhibitors in neurodegeneration." (PMID 41155556, 2025). "In brain tumors, especially H3K27-altered diffuse midline glioma (DMG H3K27-altered), ONC201 induces ClpP dependent metabolic stress and is under evaluation in clinical trials such as the recruiting PNOC022." (PMID 41155556, 2025).
glioblastoma (3 papers, 2021 to 2025). The most malignant astrocytic tumor (WHO grade IV). "In contrast, ClpP activators show anti-tumor effect in breast, ovary, colorectal, glioblastoma, and other cancers." (PMID 37046596, 2023). "Several HDACi have been exploited in combination with imipridones in CNS malignancies, and a synthetic lethality of combination of ClpP activation and HDACi is reported in glioblastoma." (PMID 37046596, 2023).
hepatocellular carcinoma (3 papers, 2024 to 2025). A malignant tumor that arises from hepatocytes. "First characterized in microbial systems and neurodegenerative diseases, ClpP is implicated in hepatic disorders such as non-alcoholic steatohepatitis (NASH) to hepatocellular carcinoma (HCC), and liver metastases." (PMID 41155556, 2025). "ONC206 inhibits hepatocellular carcinoma growth by inducing apoptosis and cytoprotective autophagy mediated by ClpP-induced mitochondrial dysfunction, with enhanced effects upon autophagy blockade." (PMID 39315094, 2024).
lung adenocarcinoma (3 papers, 2016 to 2021). A carcinoma that arises from the lung and is characterized by the presence of malignant glandular epithelial cells. "Importantly, high ClpP expression was correlated with shorter metastasis-free survival in BC patients and reduced RFS in those with lung adenocarcinoma." (PMID 32195060, 2020).
lung carcinoma (3 papers, 2016 to 2025). "Lung cancer risk was assessed for rs10420388 and rs10418574 in CLPP and rs11126435 in M1AP in the OncoArray study." (PMID 34604049, 2021). "Genetic studies suggested that polymorphisms in the ClpP gene may contribute to lung cancer susceptibility." (PMID 41155556, 2025). "A growing body of evidence recognized the crucial role of ClpP in lung cancer." (PMID 41155556, 2025). "SNPs identified in the CLPP and M1AP genes may be useful in risk prediction models for lung cancer." (PMID 34604049, 2021). "ClpP expression in cancer patients was independent of grade (colon adenocarcinoma and CNS tumors), Gleason score (prostate adenocarcinoma), histotype (lung cancer), or aggressive versus indolent lymphomas." (PMID 27389535, 2016).
neuroblastoma (3 papers, 2018 to 2025). Neuroblastoma (NB) is the most common solid, extracranial childhood tumor. "Many studies emphasize the importance of ClpP in mediating cancer cell death, including in breast cancer tissue, SK-N-SH neuroblastoma cells, and acute myeloid leukemia." (PMID 36675163, 2023). "Firstly, we observed a significant increase in ClpP and ClpX expression in immature and mature ganglion cells as compared to more malignant neuroblasts and less malignant Schwannian-stroma-dominant cell types in human neuroblastoma tissues." (PMID 36675163, 2023). "Recently, S. pneumoniae ClpP protease was shown to induce apoptosis of human neuroblastoma cells." (PMID 30059559, 2018). "Harmaline displayed moderate ClpP activation and cytotoxicity in DIPG-derived cell lines and neuroblastoma (GMB) spheroids, with stable hClpP interactions and CNS penetrance, suggesting potential for optimization." (PMID 41155556, 2025).
non-small cell lung carcinoma (3 papers, 2016 to 2025). A group of at least three distinct histological types of lung cancer, including non-small cell squamous cell carcinoma, adenocarcinoma, and large cell carcinoma. "In addition, ClpP became more prominently expressed in metastatic non-small cell lung cancer (NSCLC), compared to non-metastatic lesions, with the highest levels in brain-metastatic NSCLC." (PMID 27389535, 2016).
Parkinson’s (3 papers, 2020 to 2025). "The α-synuclein mutant A53T, linked to early on-set Parkinson’s disease, is even more prone to co-aggregate with ClpP than the wild-type α-synuclein, and has a more severe impact on the proteolytic capacity of ClpP." (PMID 33227899, 2020). "Recently, it was shown that wild-type α-synuclein in Parkinson models and in the brains of Parkinson’s patients interacts with ClpP, causing reduced ClpP levels by promoting ClpP aggregation as well as a reduction in the proteolytic activity of ClpP." (PMID 33227899, 2020). "Moreover, CLPP is helpful in reducing αSyn-induced mitochondrial oxidative stress in Parkinson’s patients by increasing the expression of superoxide dismutase-2 (SOD2)." (PMID 36834738, 2023).
staphylococcal infection (3 papers, 2017 to 2023). An infection caused by Staphylococcus. "Our findings indicate that the species-specific activators of Staphylococcus aureus ClpP are exciting therapeutic agents to treat staphylococcal infections." (PMID 36376309, 2022). "ClpP is required for pathogenesis in a systemic staphylococcal infection as well as skin abscess infection, indicating that ClpP plays important roles in S. aureus pathogenesis." (PMID 28555174, 2017). "Our results suggest that clpP mutant S. aureus directly targets PD-1 to evade immune activation and that therapeutic targeting of PD-1 may be used against certain staphylococcal infections." (PMID 37796131, 2023).
uveal melanoma (3 papers, 2016 to 2025). A melanoma derived from melanocytes of the uveal tract. "High ClpP expression in uveal melanoma tumors was correlated with increased treatment sensitivity, highlighting its potential as a predictive biomarker." (PMID 41155556, 2025).
cardiomyopathy (2 papers, 2020 to 2022). A disease of the heart muscle or myocardium proper. "In DARS2 knockout mice, which have a cardiomyopathy phenotype, deletion of the mitochondrial protease subunit CLPP is protective, providing evidence that CLPP plays a role in regulating mitochondrial translation." (PMID 33171986, 2020). "The 2 proteases CLPP and YME1L1 have a particular interest in our study, as their genetic inhibition induces cardiomyopathy." (PMID 35230976, 2022).
colorectal cancer (2 papers, 2023 to 2025). A primary or metastatic malignant neoplasm that affects the colon or rectum. "ClpP expression has been found also in colorectal cancer (CRC), a malignancy characterized by high metabolic plasticity and frequent resistance to conventional chemotherapy." (PMID 41155556, 2025).
epilepsy (2 papers, 2016 to 2018). A brain disorder characterized by episodes of abnormally increased neuronal discharge resulting in transient episodes of sensory or motor neurological dysfunction, or psychic dysfunction. "In an infant patient with sensorineural hearing loss, psychomotor retardation, and epilepsy, WES resulted in identification of a novel homozygous CLPP frameshift mutation (c.21delA)." (PMID 27899912, 2016).
Friedreich ataxia (2 papers, 2015 to 2021). An inherited condition that affects the nervous system and causes movement problems. "A mouse model of Friedreich ataxia with a striated-muscle specific frataxin knockout showed an increase in expression of the CLPP and LON proteases associated with a decrease in mitochondrial Fe-S proteins." (PMID 34280433, 2021).